CD69 (CD69 molecule)
Diseases named in the same sentence as CD69 in open-access papers (continued):
Sharing a sentence is not in itself a finding about the gene and the disease.
infection (continued). "Frequencies of CD38low cells followed the same pattern as CD69 expression on NK cells, with elevations early during infection that remained high even during convalescence." (PMID 26439909, 2016). "In this regards, IL-15 SA caused a substantially higher activation of CD4+ T cells (~ 55% CD69 expression) post infection as compared to the sham (~10%) and vehicle treated burn wound infected group (~32%)." (PMID 26859674, 2016). "The frequency of CD69+ cNK cells was increased after infection with all the strains in PEC and after RH and ME49 infections in spleen." (PMID 27721814, 2016). "Flow cytometry analysis revealed that iNKT cells had upregulated CD25 and CD69 expression and indeed displayed signs of activation in both tissues at 16–24 hours post-infection." (PMID 25615690, 2015). "As a positive control, resting CD4+ T cells were stimulated with αCD3/αCD28 activating beads in the presence of IL-2 for 72 h prior to infection, which led to significant expression of both CD69 and CD25 activation markers." (PMID 26067822, 2015). "Our data showed that infection with either lineage led to a higher expression of the activation molecule CD69 by CD4+ and CD8+ T lymphocytes as compared to media control." (PMID 26147698, 2015). "It has also been shown that upregulation of CD69 expression inhibits lymphocyte migration and T cells remain at the site of infection." (PMID 26322025, 2015). "We first showed that CD4+ and CD8+ T lymphocytes display higher expression of CD69 after infection with Y strain and Col cl1.7, showing that both strains induce T cell activation." (PMID 26147698, 2015). "This indicates that the decreased frequency of CD69+ TEM cells after infection results from a massive influx of CD69− TEM cells." (PMID 26793197, 2015). "Although we cannot exclude NK cell-mediated killing of Y. pseudotuberculosis in our in vivo models, cytotoxic responses seem less important, since only the subpopulation expressing the activation marker CD69 expanded during the infection." (PMID 26296209, 2015). "By contrast, METH increased CD69 expression of CD8+ T cells at early infection indicating increased activation." (PMID 26322025, 2015). "The expression of CD69 significantly decreased during the course of infection (CD4–LCMV—day 14 vs. day 56—**p < 0.01; CD8-LCMV—day 14 vs. day 56—*p < 0.05)." (PMID 26322025, 2015). "The kinetics of CD69 expression in both subsets of T cells decreased during the course of infection." (PMID 26322025, 2015). "Upregulation of CD69 was seen as early as one day after infection and was primarily detected in the spleen, with some expression also seen in the liver draining lymph nodes (celiac LN, portal LN and the 1st mesenteric LN)." (PMID 24854165, 2014). "Staining total RGH infected cells for CD69 early post-infection (four days) showed that the gated ‘red’ and ‘yellow’ populations expressed approximately 2.3 and 4.5 fold more CD69 than mock-infected cells, respectively." (PMID 24502247, 2014). "An expansion of CD38+ CD69+ T cells in the acute phase compared to the resolving phase of infection with an increased in mRNA expression of IFN-gamma, TNF-α and IL-4 has reflected an increment in CD3+ CD38+ CD69+ T cells." (PMID 24963498, 2014). "Similar to our in vitro observations, CD69 expression increased on iNKT cells in the lung over the course of infection." (PMID 24391492, 2014). "CD69+ T cells were elevated early after infection while HLA-DR+ and CTLA4+ T cells were elevated during the recovery phase of those who survived." (PMID 24658451, 2014). "Splenic CD4+ and CD8+ T cells expressing CD69 were increased in response to infection with PyL in WT mice." (PMID 23527234, 2013). "To detect the earliest events of priming we looked for CD69 up-regulation on the OT-I cells 24 hours after infection of mice by the three routes." (PMID 23633956, 2013).
infection (continued). "To test this we used the OT-I model again, but this time did transfers at various times after infection (day 1, 3 and 5) by i.d. or i.v. route and looked for CD69 up regulation 24 hours later." (PMID 23633956, 2013). "CD69 expression can be transient, therefore, to confirm that we had not missed cells that expressed CD69, which had then been down-regulated; we measured the expression of CD69 over time following co-culture with mDC and infection with HIV." (PMID 24339779, 2013). "After i.d. infection, priming of OT-I T cells, as indicated by CD69 up-regulation, was very low in all sites other than the cervical LN." (PMID 23633956, 2013). "A large proportion of cells expressed CD69, an activation marker observed at all stages of infection." (PMID 24348253, 2013). "Based on the mean intensity of fluorescence (MIF) analysis, CD69 expression increased 58% during infection in both T cell subsets, indicating that the activation process was present and the treatment with drugs impaired it." (PMID 23646169, 2013). "Our results showed that NK cells were activated before S. japonicum worms lay eggs (about 24 days post-infection), because the expression of CD69 on NK cells had been upregulated 3 weeks post-infection." (PMID 22235358, 2012). "Splenocytes from all mouse strains (wild-type and knockouts) expressed high levels of CD69 on CD19+ cells following infection with live influenza virus." (PMID 21998693, 2011). "Significant increases in CD69 expression occur in this population within 24 hours of secondary infection, and limited proliferation is observed." (PMID 21647373, 2011). "Activated B cells, defined asCD20+/CD3−/CD69+, weredetected on day 10 post infection (72 hours after secondary TLR stimulation)." (PMID 21559444, 2011). "We also determined that the DP cells released from thymus during the organ atrophy showed a characteristic profile of CD44 and CD69 expression similar to single-positive T cells differentiated upon infection with T. cruzi." (PMID 21858238, 2011). "In blood, there was a transient yet significant (P<0.0001) increase in percentages and absolute numbers of CD69+CD4+ T cells at 10 days of infection, but this subsequently declined." (PMID 22096538, 2011). "Marked declines in CD4+CD69+ T cells were observed in jejunum (P<0.0001) and mesenteric lymph node (P = 0.002) by 13 days of infection and declined thereafter throughout infection." (PMID 22096538, 2011). "Increased levels of CD69+ T cells were detected at 8 d.p.i. which peaked at 10 d.p.i., then declined after 13 d.p.i., but were still sustained at high levels through primary infection." (PMID 22096538, 2011). "Further, confocal microscopy demonstrated selective, productive infection of CD3+CD69+ T cells in the intestine in early infection." (PMID 22096538, 2011). "The involvement of non-conventional and conventional CD4+ T cells in the early polyclonal B cell response to P. chabaudi malaria was then investigated by analysing spleen B cells according to cellularity and CD69 expression on days 0, 4 and 7 of infection." (PMID 21814579, 2011). "Although circulating T cells lack CD69 expression in normal macaques, both CD4+ and CD8+ T cells expressing CD69 increased in blood 10 days after SIV-infection." (PMID 22096538, 2011). "CD69 was increased post-infection in both models, but with different profiles (p = 0.0002, 2-way ANOVA)." (PMID 20625554, 2010). "C57Bl/6 mice initially had higher CD69 on the surface of B cells (4.6±2.2 fold higher than controls at day 8 p = 0.002), which then decreased over the course of infection." (PMID 20625554, 2010). "Neither showed increased levels in B cells from infected mice, and indeed a small downshift in CD69 expression was evident in the population exposed to infection." (PMID 20306466, 2010).
infection (continued). "To be sure that IL-2Jc did not stimulate NK cells or NKT cells, we examined their expression of the activation markers CD69, GzmB and IFNγ, 24 hours after infection and treatment with IL-2Jc." (PMID 21170302, 2010). "CD69 expression on T cells was significantly increased compared to controls in both models and to a similar extend at day 8 post-infection (3.6±0.3 for Balb/c and 2.9±1.3 for C57Bl/6, p<0.01 compared to control, p = 0.12 between models)." (PMID 20625554, 2010). "In these murine infection models, membrane CD69 interferes with surface expression of sphingosine 1-phosphate receptor 1 and blocks B-cell egress from particular lymphoid organs." (PMID 19543531, 2009). "This percentage slightly increased during the course of infection with the exception of day 14, when only 20% of the cells were CD69+." (PMID 19436710, 2009). "To investigate the mechanism of lymphocyte activation following LDV infection we first analyzed the kinetics of CD69 upregulation on splenic lymphocytes at several time points following infection." (PMID 19568424, 2009). "Infection increased the proportion of CD69+ activated B cellsand CD4+ T cells in immune normal mice compared to IgD deficient mice." (PMID 19859584, 2009). "T-cell analysis showed that at day 3 more of the CD4+ and CD8+ T cells, recruited to the site of infection with vΔC16, were activated (CD69+) compared with controls." (PMID 18796705, 2008). "At days 4 and 6 p.i. with WT and Rev virus, ∼20 % of lung lymphocytes expressed CD69 and this percentage decreased as the mice recovered from infection (day 11 p.i.)." (PMID 18931086, 2008). "In contrast to the IFN-γ response, maximal cytotoxicity and CD69 expression on NK cells was observed 1 day post-infection." (PMID 17407097, 2007). "CD69 expression was higher across all infection-induced B cells in adults." (PMID 40834853, 2025). "In addition, systemic T-cell activation in response to the infection is indicated by upregulation of the CD69 activation marker on CD8 and CD4 T-cells in the control animals." (PMID 41390777, 2025). "However, during infection, the TRMs phenotype were CD69+CD103+, produced IFN-γ, expressed CD107a, and exhibited a longer lifespan." (PMID 41479900, 2025). "Type II C-type lectin receptor CD69 is a classical early marker of lymphocyte activation, and nuclear antigen Ki67 is widely used to trace the proliferative activity of T cells after vaccine immunization or pathogen infection." (PMID 39081314, 2024). "CD69 acts as a non-specific signal associated with rapid immune activation following infection and has been associated with successful vaccination." (PMID 38675751, 2024). "Analysing these phenotypes during in vivo infection, knockdown or mutation of Rv0884c did not significantly change the percentage of CD69+CD8+ T cells in the lung tissues of the infected mice." (PMID 38806671, 2024). "Thus, restoring IL-15 increases the numbers of inactive, but has little effect on CD69+ NK cells during infection in Ifne-/- mice, indicating that IFNε and its IL-15-independent effects are required for local activation." (PMID 38263527, 2024). "Given that RSV is cleared from the lungs within 10 days of infection, and the mice were allowed to recover for 6 weeks, the observed downregulation of CD69-expressing CD8+ T cells in the Peyer’s patches might reflect a retracted CD8+ TRM pool." (PMID 39451246, 2024). "We speculated that different infection kinetics of these virus strains might result in varying NK cell responses and hence monitored CD69 levels at three designated time points post inoculation." (PMID 36765035, 2023). "This was supported by the upregulation of the NF-kB inhibitor genes NFKBIA and NFKBIZ, the AP-1 transcription factor complex genes FOS, JUN, FOSB and JUNB as well as other NF-kB target genes such as TNFAIP3, RELB, NR4A2, DUSP1 and CD69 in response to infection." (PMID 37700317, 2023).
infection (continued). "A small increase in CD69+ NK cells was observed in the lungs only at 24 hours and 72 hours, but no increase of Perforin+ and Granzyme B+ cells was detected at both 24 and 72 hours post-infection (MFI in S2C and S2D)." (PMID 37486946, 2023). "During the chronic stage of infection in the CNS, TCR activation was associated with large scale transcriptional changes and the acquisition of an effector T cell phenotype as well as the generation of a population of CD103+ CD69+ Trm like cells." (PMID 35727849, 2022). "Interestingly, when IFN-α treated Mavs-/- mice were re-infected 3 weeks after primary infection, CD69+ CD103+ CD8+ TRM cell expansion was recovered in the lung and airways." (PMID 35108347, 2022). "HIV-1-induced CD69 upregulation was abrogated by suppressing infection with the fusion inhibitor T20 or by treating cells with ruxolitinib, which blocks IL-7-mediated JAK-STAT signaling, demonstrating that the enhanced CD69 induction requires both infection and cytokine signaling." (PMID 35417711, 2022). "All subsets also displayed high CD69 expression during secondary infection (day 5 pri)." (PMID 36159876, 2022). "In addition, the expression of CD69 molecules associated with T cell activation in CD3+CD4+ T cells and CD3+CD8+ T cells was also opposite to the trend of MDSCs during infection of S. japonicum (p < 0.05)." (PMID 36279265, 2022). "Thus, influenza virus infection results in the development of antigen-specific, lung-resident CD4+CD69+CD11a+ T cells that persist at least seven months after infection." (PMID 36275685, 2022). "In addition, staining of unstimulated T cells for the transcription factor RORγt which is essential for the differentiation of Th17 cells, revealed that over 36% of CD69+ TRM cells from B. pertussis-infected mice expressed RORγt on day 28 post infection." (PMID 33976385, 2021). "During the acute phase of the infection, iNKT deficiency was associated with a lower frequency of CD69-expressing CD8+, but not CD4+, T cells indicating their suboptimal activation." (PMID 33954206, 2021). "(E) CD69 and HIF1α was determined at day 1.5 post-infection (pi)." (PMID 34396954, 2021). "CD69 is a canonical marker of tissue resident memory CD8+ T-cells 24 that are established during resolution of primary infection and provides an important first line of defence for the peripheral tissues upon exposure to the same or similar antigens (for review, see 28)." (PMID 32226549, 2020). "CD4+ TRM cells share many cardinal features of CD8+ TRM cells—they populate barrier sites and mucosal organs (e.g., lung, skin, salivary glands, intestine), they mediate local protection against infection, they phenotypically express CD69 and CD11a and share a core transcriptional signature." (PMID 32858901, 2020). "CD69 expression on these NK cells also rapidly enhanced following re-infection." (PMID 32626664, 2020). "Furthermore, we observed that HIV even further upregulated CD69 upon infection, similar to what has been observed in a cell line." (PMID 32452381, 2020). "In contrast, infection by O. tsustugamushi has been showed to be correlated to an increase in NK cells; both CD69+ and CD69− NK cells were found in patient blood samples, but, importantly, NK CD69+ cells produce a larger amount of IFN-γ than CD69− ones." (PMID 32751625, 2020). "In fact, since HIV infection per se could induce up-regulation of CD69 on infected cells from peripheral blood, we determined the dynamics of CD69 expression and HLA-DR over 10 days of infection in cervical tissue." (PMID 31628331, 2019). "Furthermore, natural infection or immunization with the wP vaccine induced CD69+CD4+ TRM cells that secreted IL-17, IFN-γ or both cytokines, indicative of polyfunctional memory T cells." (PMID 30866771, 2019). "To determine whether NK cells are an activated phenotype in response to Cpn infection, we measured the expression of two early activation markers, CD69 and CD25, on NK cells in a kinetic manner." (PMID 31236064, 2019).
infection (continued). "In addition, we separated CD69+ and CD69− CD4+ T cells from fresh cervical suspensions, which we immediately infected to evaluate infection (p24) and CD69 expression." (PMID 31628331, 2019). "Interestingly, CD8+ T cells expressing CD103 and CD69, which indicate a tissue-resident memory (TRM) CD8 T cell phenotype and are associated with controlling tissue immunity after infection, were enriched in the islets of 2H7-treated mice." (PMID 29594371, 2018). "The fold-change analysis of CD69 gene expression indicates that the T cell activation is much stronger in RMs than that in SMs at 10 days after SIV infection related to that before infection." (PMID 27280726, 2016). "Finally, it has been suggested that CD69 plays an immunoregulatory role by preventing infection-induced immunopathology." (PMID 26989699, 2016). "The expression of CD69 on CD56bright NK cells in HIV-HCV co-infected group was closer to HCV mono-infected group whereas the CD95 expression behaved more similar to HIV treated mono-infected group thus showing imprints of either infection." (PMID 27091211, 2016). "At the peak of infection, the proportion of NK cells expressing the early activation marker CD69+ was significantly increased in all patients and reached 72±35% in DENV-2, 58±21% in CHIKV+ and 42±5% in CHIKV/DENV-2 co-infected patients, as compared to 15±6% in healthy Gabonese controls." (PMID 26938618, 2016). "Furthermore, we adoptively transferred purified iNKT cells into 7-day-old WT mice and CD1d-/- mice and determined the CD69 expression levels of iNKT cells upon EV71M infection." (PMID 25615690, 2015). "In order to determine if exposure to monocytes infected with Y strain and Col cl1.7 led to differences in lymphocyte activation, we analyzed the expression of the activation molecule CD69 and cytokines in lymphocytes after 72 hours of infection with both lineages." (PMID 26147698, 2015). "Also, compared to P25 T cells, a greater proportion of DN1 T cells in the lung and spleen expressed CD69 and underwent cell division at day 15 post-infection." (PMID 26652001, 2015). "The reasons for this dynamic regulation of CD69 are not clear but it is probable that there might be a period of time later during infection when T cells are refractory to further upregulation of CD69." (PMID 26322025, 2015). "However, CD4+ T cell activation, as measured by expression of CD69, was higher in IN-inoculated mice than FP-inoculated mice throughout the course of infection and significantly greater 8 dpi." (PMID 24922480, 2014). "Interestingly, upon infection this effect on NK cells is completely neutralized in terms of cell frequency, CD69 expression and functionality with respect to IFN-γ production." (PMID 25108672, 2014). "IL-22+ (and IL-22−) NK cells upregulated the activation marker CD69 upon infection." (PMID 24721575, 2014). "Furthermore, a larger proportion of infection-induced Tregs showed a higher activation state indicated by increased early activation marker CD69 expression after 40 h and 3 days p.i.." (PMID 25108672, 2014). "Thus, the efficient recognition of Mtb antigens and successful containment of the infection were likely associated with upregulation of CD28, CD69 and other genes of the T cell activation network in the CDC1551-infected rabbit lungs." (PMID 23448601, 2013). "Increasing expression of CD69 suggested activation of NK cells after SIV/SHIV infection." (PMID 23424655, 2013). "Furthermore, the expression of CD69 in T cells after in vitro stimulation with mycobacterial antigens or antigens from the sites of infection indicates previous exposure to M. tuberculosis." (PMID 23824716, 2013). "Similarly, treatment of J774A.1 cells with AA or infection with mycobacteria induces NFkB activation and surface expression of CD69 within one hour; p38 MAP kinase activation in these cells is noted by 3 hours." (PMID 23958185, 2013).